DUX4L3 (double homeobox 4 like 3 (pseudogene))
Description:
May be involved in transcriptional regulation.
Gene: Unprocessed pseudogene on chromosome 4 (190,087,705 to 190,088,979, forward strand). Ensembl gene ENSG00000281627.
Subcellular location: Nucleus
Diseases named in the same sentence as DUX4L3 in open-access papers:
DUX4L3 is named in the same sentence as 1 disease in open-access papers, as found by Europe PMC text mining. Sharing a sentence is not in itself a finding about the gene and the disease. The quoted sentences say what the papers report.
neuroblastoma (1 paper, 2022). Neuroblastoma (NB) is the most common solid, extracranial childhood tumor. "Using SVR‐NB, 35 lncRNAs have been identified, showing that 4 lncRNAs (LOC729770, CXCR2P1, LOC387720, and DUX4L3) may affect the overall survival of neuroblastoma patients." (PMID 35592755, 2022).